PAK1 (p21 (RAC1) activated kinase 1)
Diseases named in the same sentence as PAK1 in open-access papers (continued):
Sharing a sentence is not in itself a finding about the gene and the disease.
pancreatic cancer (continued). "In PAK1 WT mice, cannabis oil (CBD:THC at 1:1) reduced the pancreatic tumour growth by decreasing tumour volume and tumour weight." (PMID 33126623, 2020). "Reduction of PAK1 expression by shRNA knock-down inhibited proliferation of the PANC-1 and MiaPaCa-2 pancreatic cancer cell lines, likely through modulation of the AKT pathway." (PMID 26774265, 2016). "However, the role of PAK1 in pancreatic cancer remains largely unknown." (PMID 25182632, 2014). "PAK1 and PAK4 double knockout (PAK1&4KO) suppressed pancreatic tumour volume in a SCID mouse model, but not tumour weight, suggesting that PAK4KO-induced increased tumour weight compromised PAK1KO-reduced tumour weight." (PMID 41228228, 2025). "PAK1&4KO markedly increased ICAM-1 and VCAM-1 expression in pancreatic tumour tissues while decreasing the expression of ICAM-1 and VCAM-1 by cancer cells, indicating that PAK1&4KO upregulated the ICAM-1 and VCAM-1 in tumour stromal cells rather than the tumour cells." (PMID 41228228, 2025). "Interestingly, in pancreatic cancer, PAK4 exhibited the highest frequency of alterations (10%), a notable increase compared to PAK2 (4%) and PAK3 (1%), while PAK1, PAK5, and PAK6 were altered in fewer than 1% of cases." (PMID 39756822, 2025). "PAK1 and PAK4 have received the most attention because they are most frequently overexpressed; however, each of the five PAKs has been shown to be important in pancreatic cancer growth." (PMID 40001881, 2025). "Pancreatic cancer: PAK1 and PAK4 are known to be overexpressed in pancreatic cancer." (PMID 36830998, 2023). "However, the efficacy of PAK1, TWIST1, or CD44 inhibition for pancreatic cancer treatment will have to be determined in further pre-clinical and clinical studies." (PMID 33578795, 2021). "βPix/COOL-1 has also been shown to interact with PAK1 (p21-activated kinase) and STIL (SCL/TAL1-interrupting locus), to promote actin remodelling and promote cancer cell migration in pancreatic cancer models suggesting a potential mechanism for the βPix/COOL-1 mediated invasion evident in GBM." (PMID 33256106, 2020). "We confirmed that PAK1 was not expressed in normal pancreatic acinar or ductal cells, which are the likely progenitors of pancreatic cancer." (PMID 26774265, 2016). "Although growing evidence shows that p21-activated kinase 1 (PAK1) plays a crucial role in pancreatic cancer, its role has not been fully elucidated." (PMID 26774265, 2016). "The amount of active PAK1 was significantly reduced when treated with FRAX597 alone compared to control in all pancreatic cancer cell lines without affecting the amount of total PAK1." (PMID 26774265, 2016). "Expression of PAK1, and of the phosphorylated, active form of PAK1, was detected in low levels in the normal HPDE cell line and was significantly lower when compared to all the pancreatic cancer cell lines." (PMID 26774265, 2016). "Combination of the PAK1 inhibitor, FRAX597, with gemcitabine resulted in increased inhibition of PAK1 activity in some, but not all, of the pancreatic cancer cell lines tested." (PMID 26774265, 2016). "Downregulated PAK1 in pancreatic cancer cells displayed decreased proliferation and transforming properties, and PAK1 diminished cells could not form xenografts in athymic mice." (PMID 35566098, 2022). "Their findings suggest a novelty for the cannabinoids in which KRAS, an undruggable target expressed in many lethal cancers can be supressed through targeting PAK1 and the suppression of PDL-1 could be enhanced for immune checkpoint blockade therapy in pancreatic cancers." (PMID 34259916, 2021). "The role of PAK1 in pancreatic cancer and its therapeutic potential have not been fully elucidated." (PMID 26774265, 2016). "However, the IC50 values for either proliferation or migration/invasion did not significantly correlate with the amount of active PAK1 in the pancreatic cancer cells (data not shown)." (PMID 26774265, 2016).
pancreatic cancer (continued). "Thus, PAK1 signalling through AKT and ERK pathways is dependent on the cancer type, and our study suggests that PAK1 mediates pancreatic cancer cell growth through the AKT pathway rather than the ERK pathway." (PMID 26774265, 2016). "Our results indicate that PAK1 may play a critical role in the initial phase of carcinogenesis rather than tumor development or metastasis in pancreatic carcinoma." (PMID 25182632, 2014). "However, the question of whether shikonin executes anti-pancreatic cancer activity through PAK1 has not been fully revealed yet." (PMID 35566098, 2022). "This may also indicate that PAK1 does not promote tumor metastasis in pancreatic cancer patients." (PMID 25182632, 2014). "However, there are no reports on the clinical significance of PAK1 in human pancreatic cancer." (PMID 25182632, 2014). "However, they did not compare PAK1 expression levels among pancreatic cancer tissues." (PMID 25182632, 2014). "PAK signalling influences endothelial behaviour and immune functions; however, the specific roles of PAK1 or PAK4 in vascular reprogramming, hypoxia, and the gemcitabine response have not been fully addressed in pancreatic cancer." (PMID 41294859, 2025).
colorectal cancer (32 papers, 2011 to 2026). A primary or metastatic malignant neoplasm that affects the colon or rectum. "In cervical cancer and colorectal cancer, PAK1 can promote HIF1-α activation to adapt to oxygen-deficient conditions." (PMID 32863957, 2020). "However, in the studies on breast and colorectal cancers, the p-value of the association between PAK1 levels and recurrence-free survival rate was 0.05, which is statistically ambiguous." (PMID 33261184, 2020). "The proteins DDX17, MPG and PAK1 have been linked to colorectal cancer." (PMID 22087225, 2011). "NCK1 promotes angiogenesis in cervical squamous cell carcinoma and ovarian cancer via the RAC1/PAK1/MMP2 axis and in colorectal cancer via the NCK1/STAT3/PAK1/ERK axis." (PMID 40001545, 2025). "In contrast, PAK1, encoding the serine/threonine p21-activated kinase, plays a role in KRAS-driven colorectal cancer cell proliferation." (PMID 38213716, 2024). "Another study revealed that GCB suppresses the growth of colorectal cancer cells through the inhibition of β-catenin and hypoxia-inducible factor 1-α, which is mediated by the down-regulation of the PAK1 pathway." (PMID 33567682, 2021). "PAK1 confers β-catenin-mediated stemness in non-small cell lung cancer and induced cancer stem cell marker of colorectal cancer." (PMID 31658701, 2019). "Our previous study showed that PKC-ζ regulates the growth of colorectal cancers cells via PKC-ζ/Rac1/Pak1/β-Catenin pathway." (PMID 30417717, 2019). "Here the authors study an inducible peptide mimicking the auto-inhibitory domain of Pak1 and show promising anti-tumor effects in a mouse model of colorectal cancer." (PMID 30150766, 2018). "Our recent report, that the PAK inhibitor PF-3758309 suppressed xenograft CRC cell growth in SCID mice by inhibition of PAK1 activity, suggested that PAK1 is the target of PF-3758309 that mediates its inhibitory effect on colorectal cancer growth." (PMID 28629331, 2017). "We have previously reported that PAK1 stimulates growth and metastasis of colorectal cancer (CRC), through activation of multiple signalling molecules including ERK, AKT and β-catenin." (PMID 28629331, 2017). "Our group has previously found that PAK1 mediated growth of colorectal cancer cell lines by both ERK and AKT pathways, while another group has found that PAK1 signalled preferentially through the ERK pathway to control skin cancer growth." (PMID 26774265, 2016). "PAK1 was expressed in colorectal cancer cell lines including Colon26L5, HCT116, HCT15, HT29, and SW620 cells." (PMID 25074784, 2014). "Another study demonstrated that PAK1 induced colorectal cancer metastasis via extracellular signal-regulated kinase (ERK)-dependent phosphorylation of focal adhesion kinase (FAK)." (PMID 25182632, 2014). "PAK1 knockdown was shown to inhibit the activation of β-catenin in colorectal cancer, thereby inhibiting Wnt/β-catenin signaling and proliferation." (PMID 25074784, 2014). "This is consistent with previous reports, in which, knockdown of PAK1 in colorectal cancer cells by shRNA suppressed cell proliferation via the ERK and AKT pathways." (PMID 25074784, 2014). "Overexpression of PAK1 was also found in colorectal cancer, and PAK1 expression was significantly increased in adenomas, invasive carcinomas, and lymph node metastases compared to normal colon." (PMID 25182632, 2014). "A recent study showed that PAK1-dependent MAPK pathway activation is required for colorectal cancer cell proliferation." (PMID 24279335, 2013). "Overexpression of PAK1 has been detected in colorectal cancer and PAK1 expression closely correlated with the aggressive progression of colorectal cancer." (PMID 24279335, 2013). "P21-activated kinase 1 (PAK1) plays an oncogenic role in colorectal cancer (CRC)." (PMID 41459112, 2026). "Moreover, the correlation between CD44 and PAK1 activation was reported before in colorectal cancer, where PAK1 activation correlated to CD44 expression levels and promoted chemoresistance." (PMID 35853934, 2022).
colorectal cancer (continued). "Moreover, PAK1 is extremely vital for MAPK pathway activation e.g. in colorectal cancer which strengthens the inference on this issue." (PMID 33718178, 2021). "Therefore, we first assessed PAK1 expression levels in mouse and human colorectal cancer cell lines by Western blot." (PMID 25074784, 2014). "In addition, knockdown of PAK1 enhanced EOPK-mediated alterations of actin cytoskeleton in HCT116 colorectal cancer cells." (PMID 25074784, 2014). "Our findings suggest that EOPK exerts its anticancer activity via the inhibition of PAK1 expression, suggesting it may be a potent chemotherapeutic agent for colorectal cancer." (PMID 25074784, 2014). "PAK1 expression increases with the progression of colorectal cancer." (PMID 25074784, 2014). "In addition, PAK1 overexpression occurs in a variety of human cancers, including breast, ovarian, and colorectal cancer." (PMID 25074784, 2014). "A recent study revealed that PAK1 expression increased with the progression of colorectal cancer." (PMID 25182632, 2014). "Additionally, PAK1 expression is significantly increased in colorectal cancer and closely correlates with aggressive disease progression." (PMID 24279335, 2013). "Additionally, PAK1 expression is reportedly elevated in malignant progression of human colorectal carcinoma." (PMID 22848689, 2012). "Thus, PAK1 may play an important role in cell growth, adhesion, migration, and survival in colorectal cancer, through the activation of AKT, ERK and β-catenin." (PMID 25074784, 2014). "P21-activated kinase 1 (PAK1) stimulates growth and metastasis of colorectal cancer (CRC) through activation of multiple signalling pathways." (PMID 28629331, 2017). "EOPK remarkably suppressed the phosphorylation of AKT, ERK, and PAK1, as well as the expression of β-catenin in HCT116 colorectal cancer cells." (PMID 25074784, 2014). "Finally, the six selected genes (SIRT3, PIK3CA, ITGA3, DAPK1, PAK1, and CASP3) have been reported in colorectal cancer." (PMID 38213716, 2024). "F. nucleatum promotes colorectal cancer cell proliferation and tumorigenesis by activating Toll-like receptor 4(TLR4) signaling, which upregulates nuclear factor-κB, as indicated by increased MicroRNA-21 expression or the TLR4/p-PAK1/p-β-catenin S675-cascade signaling pathway." (PMID 31993418, 2019). "However, we did not discover a significant correlation between PAK1 overexpression and invasion depth in current study, which is disagreeable with findings studied in gastric and colorectal cancers." (PMID 24236193, 2013). "Based on previous findings and published validated targets for miR-7 such as EGFR, PAK1, RAF1, IRS1/2 and CD98, it is fair to hypothesize that this miR may be involved in regulating intracellular signaling, growth and differentiation of colorectal cancers." (PMID 22529906, 2012).
colon carcinoma (25 papers, 2008 to 2024). "In colon cancer, downregulation of PAK1 is associated with reduced cell proliferation and β-catenin levels." (PMID 36594908, 2021). "For instance, PAK1 activation implicated in Wnt/β-Catenin drives early phases of oncogenesis and cancer growth in colon cancer." (PMID 32863957, 2020). "In recent years, it has been reported that p21-activated kinase 1 (PAK1) is associated with colon cancer progression and metastasis." (PMID 28423670, 2017). "AZA197 suppressed colon cancer cell proliferation, cell migration and invasion and increased apoptosis associated with down-regulation of the PAK1 and ERK signaling pathways in vitro." (PMID 24279335, 2013). "It was found that advanced grades of colon carcinoma correlated with increased immunostaining for Pak1 (a driver of macropinocytosis), CD63 (a MVB/late endosome marker), and V0a3 (a lysosomal V-ATPase marker)." (PMID 37902809, 2023). "ABT-737 is a small-molecule inhibitor that represses Bcl-2/Bcl-XL, resulting in the inhibition of RNAi of PAK4 and PAK1 in HCT116 colon cancer cells." (PMID 35409064, 2022). "Studies found that inhibition of PAK4 and PAK1 suppresses the KRAS and BRAF mutation in colon cancer in vitro." (PMID 35409064, 2022). "In line with this, downregulation of PAK1 in colon cancer cells was demonstrated to reduce beta-catenin levels and cell proliferation." (PMID 34066419, 2021). "Accordingly, PAK1 overexpression partially overcomes the 5-fluoro-uracile (5-FU) -induced growth inhibition of human colon cancer cells xenografted in scid mice, whereas PAK1 inhibition acts in synergy with 5-FU treatment." (PMID 32178475, 2020). "A similar kinase-independent phenotype, attributed to the improved scaffolding of proteins within the MAPK pathway, is reported in colon cancer cell lines overexpressing a kinase dead version of PAK1." (PMID 29875996, 2018). "To assess the contribution of PAK1 to oncogenic signaling pathways in colon cancer cells, we knocked down PAK1 expression with siRNA." (PMID 25074784, 2014). "The expression of PAK1 in colon cancer cells promoted transformation through facilitating the ERK/MAPK (mitogen-activated protein kinases) pathway and enhanced cell migration and survival by stimulating AKT." (PMID 25182632, 2014). "AKT and ERK activities have been decreased by reduction of PAK1 expression leading to decreased cell proliferation, migration/invasion and survival in colon cancer." (PMID 24040362, 2013). "ERK activity is decreased by PAK1 deactivation leading to decreased cell proliferation, migration/invasion and survival in colon cancer." (PMID 24279335, 2013). "Intriguingly, a recent study has shown that Pak1 expression is upregulated in adenomas and invasive colon cancers relative to normal colonic epithelium." (PMID 18826597, 2008). "Also in colon cancer, PAK1 is a critical component of the Akt pathway, which promotes cell survival." (PMID 36594908, 2021). "Our previous study found that RAC1 could significantly induce the EMT of colon cancer cells, which may be related to the positive regulation of Rac1/PAK1/LIMK1/Cofilins signaling pathway." (PMID 32411607, 2020). "Collectively, our results indicate that Fn may primarily activate β-catenin signaling through its LPS, subsequently involving a TLR4/PAK1 cascade in colon cancer cells." (PMID 28423670, 2017). "Interestingly, we found that EOPK treatment significantly reduced PAK1 expression in several colon cancer cells." (PMID 25074784, 2014). "Furthermore, the ERK-dependent pathway is required in PAK1-mediated colon cancer cell migration and invasion." (PMID 24279335, 2013). "Moreover, colon cancer cells overexpressing PAK1 have higher migration rates, whereas down-regulation of PAK1 significantly reduces cell migration." (PMID 24279335, 2013). "Alternatively, Rac1 may exert its stimulatory effects on β-catenin/TCF-mediated transcription in colon cancer cells though the downstream effector protein Pak1." (PMID 18826597, 2008).
colon carcinoma (continued). "Similarly, PAK1/2 phosphorylation was also dose-dependently and significantly reduced up to 72.8 ± 15.8% (P < 0.014) on AZA197 treatment of HT-29 cells without influencing total PAK protein expression, indicating that Cdc42 inhibition blocks the PAK1 signaling pathway in these colon cancer cells." (PMID 24279335, 2013). "To confirm the successful induction of the 6 model genes (SIRT3, PIK3CA, ITGA3, DAPK1, PAK1, and CASP3), we gathered a set of 39 colon cancer tissue samples." (PMID 38213716, 2024). "As a result, further investigation identified that PAK4 and PAK1 suppression were responsible for 95% and 80% cell proliferation, respectively, in HCT116 colon cancer cell lines alone." (PMID 35409064, 2022). "Combined, these data suggest that EOPK suppresses cell growth and migration via the inhibition of PAK1, AKT, and ERK signaling in colon cancer cells." (PMID 25074784, 2014). "We provide evidence that Cdc42 inhibition by AZA197 treatment suppresses proliferative and pro-survival signaling pathways via PAK1-ERK signaling and reduces colon cancer cell migration and invasion." (PMID 24279335, 2013). "Interestingly, when PAK4 and PAK1 were treated simultaneously, only PAK4 responded for seven colon cancer cell lines in the cell proliferation assay." (PMID 35409064, 2022). "PAK1 also interacts with β-catenin to promote β-catenin/TCF4 activation in gastric epithelial cells and it phosphorylates β-catenin at Serine 675, which increases the stability and transcriptional activity of β-catenin in colon cancer cells." (PMID 27713506, 2016).